AURKA (aurora kinase A)
Diseases named in the same sentence as AURKA in open-access papers (continued):
Sharing a sentence is not in itself a finding about the gene and the disease.
breast cancer (continued). "Tan IIA suppresses the proliferation of AML cells (HL-60 and THP-1), glioma cells, esophageal cancer cells (EC109), breast cancer cells, and NSCLC cells through targeting miR-497-5p/Akt3, miR-122/PKM2, miR-16-5p/TLN1, miR-125b/STAR13, and let-7a-5p/aurora kinase A (AURKA), respectively." (PMID 36172186, 2022). "SMAD5 appeared up-regulated but not Aurora kinase A (AURKA), which cooperates to promote chemoresistance in breast cancer therapies." (PMID 36430510, 2022). "Aurora kinase A (AURKA) mRNA expression was identified as a biomarker of PP2A-dependent growth factor activation, and was used to classify breast cancer cases into a novel therapeutic class of tumors with predicted susceptibility to the restoration of PP2A activity using FTY720 (unpublished data)." (PMID 34768523, 2021). "However, in breast cancer cells (MCF-7, MDA-MB-231, and SK-Br3), microarray analysis in response to hypoxia illustrates that hypoxia downregulates AURKA." (PMID 34062959, 2021). "However, ER + advanced breast cancer patients with intrinsic resistance to endocrine therapy and treated with combined CDK4/6i and endocrine therapy whose tumors expressed low AURKA exhibited significantly shorter PFS." (PMID 33398005, 2021). "More interestingly, elevated expression of AURKA predicts poor survival in ERα-positive but not in ERα-negative breast cancers." (PMID 33451333, 2021). "Although there is no direct evidence that tanshinone I can directly target AURKA, it exhibits potent effects on growth inhibition of colon cancer, lung cancer and breast cancer cells through downregulating AURKA expression." (PMID 33451333, 2021). "The same observation was reported in breast cancer, where AMG 900 efficacy was not linked to AURKA protein and mRNA expressions or classic molecular specific subtype." (PMID 32138169, 2020). "Nuclear AURKA acts as a transcriptional factor that activates the MYC promoter to enhance breast cancer stem cell phenotype independent of its kinase activity." (PMID 31920463, 2020). "Aurora Kinase A (AURKA) overexpression has been previously reported to increase the expression of slingshot kinase 1 (SSH1) resulting in increased cofilin activation and migration of breast cancer cells." (PMID 31035605, 2019). "Dual targeting of AURKA and PAK1 may be a promising therapeutic strategy for treatment of breast cancer, with a particular effectiveness in luminal and HER2-enriched tumor subtypes." (PMID 31254157, 2019). "AURKA promotes epithelial-mesenchymal transition and stem cell properties of ER + breast tumors in a mechanism involving overexpression of HER2, while PAK1 is an essential mediator of HER2 signaling in mammary tumors dependent on this protein." (PMID 31254157, 2019). "Of relevance to breast cancer, both AURKA and PAK1 phosphorylate estrogen receptor alpha (ERα) (on serines S118 (PAK1) and S305 (PAK1 and AURKA)) supporting ligand-independent transcription of ERα-dependent genes promoting proliferation, invasion, and endocrine resistance." (PMID 31254157, 2019). "Based on these activities of AURKA and PAK1, we hypothesized that combined inhibition of both could have synergistic anti-tumor effects in breast cancer." (PMID 31254157, 2019). "While it is clear that AURKA is one of the best single genes for predicting breast cancer prognosis, it does not necessarily represent the optimal biomarker." (PMID 30390622, 2018). "Forced expression of the mitotic Aurora kinase A (AURKA), which promotes breast cancer metastases, failed to restore the invasive capacity of NOTCH3-null cells, demonstrating that NOTCH3 expression is required for an invasive phenotype." (PMID 30180881, 2018). "Both knocking down of AURKA and FOXM1 could reduce tumour initiation ability of breast cancer cells." (PMID 28114286, 2017). "To further investigate whether FBXW7 expression correlated with its substrates in breast cancer tissues, we decided to study the protein levels of Cyclin E, MCL1, AURKA and PLK1 in these samples." (PMID 27409838, 2016).
breast cancer (continued). "This hypothesis was further corroborated by the correlation between AurkA and CD44, a marker for breast cancer stem cells (Pvalue = 0.00001) in 26 out 32 breast cancer samples." (PMID 27341528, 2016). "To analyze FBXW7 expression and its relation to the relative abundance of substrates, and with prognostic variables in breast cancer, we performed immunohistochemistry for FBXW7, AURKA, Cyclin E, MCL1 and PLK1 in tissue microarrays containing up to 296 samples of breast carcinomas." (PMID 27409838, 2016). "The cytoplasmic AURKA level was lower in breast cancer cells compared with the non-transformed MCF-10A cells." (PMID 26782714, 2016). "ENMD-2076 is another specific AURKA inhibitor, currently in phase 2 for ovarian and breast cancers (NCT01914510, NCT01639248, NCT01104675) that has not been tested in GI cancers." (PMID 25987188, 2015). "These authors used AURKA in addition to ER and HER2 to robustly define breast cancer subtypes." (PMID 23186136, 2012). "Furthermore, expression levels are higher in metastases of breast cancer tumors (p < 0.001 and p < 0.01, for UBE2C and AURKA respectively), which again points to a role for these proteins in metastatic behavior." (PMID 20630075, 2010). "Consequently, AURKA and FOXM1 collaboratively contribute to the aggravation of breast cancer." (PMID 40003882, 2025). "Interestingly, both AURKA and TPX2 are included in this minimal signature, which directly correlates with an increased DNA index (aneuploidy vs. euploidy) in samples from breast cancer patients, and is able to stratify grade 2 tumours for a good or bad prognosis." (PMID 39195284, 2024). "However, how oncogenic AURKA poses the impact on modulating breast cancer-related RNA splicing has not been reported." (PMID 37415951, 2023). "After observing that AURKA is at a FRET-compatible distance with ATP5F1A and ATP5F1B, we asked whether these proteins could be a nexus regulating cell cycle progression and ATP levels in breast cancer cells." (PMID 37386025, 2023). "It is worth noting though that the in vitro translation assay used—in rabbit reticulocyte lysate—may not recapitulate the translational regulation of AURKA mRNA occurring in breast cancer cells." (PMID 36067794, 2022). "Disorders in cell-cycle-related pathways have key influences on breast cancer prognosis, and our feature selection result highlights that CDK1, CDK4, AURKA, and PLK1 may play vital roles in the complex cell cycle regulatory network, which in turn affects breast cancer prognosis." (PMID 34290286, 2021). "Therefore, the close interaction of TACC3 with CKAP5, AURKA, and CDC20 may suggest the role of TACC3 in the progression of breast cancer, although future mechanistic studies are needed to verify this possibility." (PMID 34149795, 2021). "Binding of NEDD9 to AURKA, which appears to involve NEDD9 serine (Ser) 296 and the N-terminal domain of AURKA, suppresses proteasomal degradation of AURKA promoted by the ubiquitin ligase anaphase-promoting complex/C (APC/C) in MDA-MB-231 cells, a human breast cancer cell line." (PMID 34944109, 2021). "This conditional analysis suggests that the GReX of AURKA, CAPN13, and SERPINB5 may be associated with breast cancer-specific survival independent of the GWAS-identified variant." (PMID 32079541, 2020). "Further inspection of the modules found that three of these modules are related to known breast cancer related processes such as epithelium development, chromosome organization, and mitotic cell cycle including well-known breast cancers genes such as NCOA3, AURKA, MKI67, and FOXA1." (PMID 30906311, 2019). "It was known that the two kinases AURKA and PLK1 were upregulated in a number of tumors including colorectal and breast cancer, as a result of perturbations in centrosome function and spindle assembly that could promote tumorigenesis by enhancing genome instability." (PMID 24876664, 2014).
breast cancer (continued). "We have shown that AURKA is prognostic in breast cancer patients who did not receive chemotherapy." (PMID 23186136, 2012). "Currently, most research efforts have been focused on AURKA protein, and evidence indicates that AURKA expression, but not AURKB expression, is predictive of patient survival in breast cancer." (PMID 23228031, 2012). "Here we found that AURKA could not regulate the expression of hnRNPK, but could recruit hnRNPK to form splicing co-factors that facilitate RBM4 exon skipping in breast cancer." (PMID 37415951, 2023). "High levels of Bcl-xL or Aurora A have been previously correlated with poor overall survival (OS) and short progression-free survival (PFS) in breast cancer, including TNBC, but a correlation between co-expression of AURKA and BCL2L1 and TNBC patient survival has not yet been reported." (PMID 36077449, 2022). "On the contrary, expression of GFP-AURKA in vMCF-7Raf-1 1GXCRISPR-NOTCH3 cells failed to restore their invasive ability, demonstrating that NOTCH3 expression is required to mediate AURKA-induced breast cancer cells’ aggressiveness." (PMID 30180881, 2018).
neuroblastoma (96 papers, 2011 to 2025). Neuroblastoma (NB) is the most common solid, extracranial childhood tumor. "We have demonstrated that AURKA inhibition by alisertib or LY3295668 in combination with selective radiation therapy with 131I-MIBG or radiation is active in high-risk neuroblastoma." (PMID 38869684, 2024). "The result of SA-β-gal staining indicated that exogenous MYCN expression weakened the occurrence of senescence, indicating that MYCN degradation resulting from AURKA inhibition is a possible cause of neuroblastoma cellular senescence." (PMID 31920463, 2020). "It has been shown that AURKA is widely overexpressed in various tumors, including neuroblastoma (NB), and has been linked to a poor prognosis." (PMID 31920463, 2020). "To evaluate the associations between the SNPs in the AURKA gene and neuroblastoma susceptibility, we conducted this case–control study with 393 neuroblastoma cases and 812 control subjects from the Chinese population." (PMID 29678897, 2018). "Future studies with larger sample sizes and different ethnicities are required to further clarify the effect of AURKA SNPs on the risk of neuroblastoma." (PMID 29678897, 2018). "We conducted the present case–control study with a total of 393 neuroblastoma patients and 812 control subjects to investigate the impact of three AURKA SNPs on the risk of neuroblastoma in Chinese populations." (PMID 29678897, 2018). "Overexpression of the AURKA gene in neuroblastoma is associated with high-risk, late-stage tumors, unfavorable histology, MYCN amplification, and in general decreased survival of neuroblastoma patients." (PMID 30027525, 2018). "Aurora kinase A is a serine/threonine kinase that has been associated with poor prognosis in neuroblastoma." (PMID 26771642, 2016). "In neuroblastoma, high AURKA expression is associated with poor patient survival, so that the interaction of a tumor suppressor with AURKA was of immediate interest." (PMID 22305495, 2012). "Aurora kinase A (AURKA) has been implicated in the regulation of cell cycle progression, mitosis and a key number of oncogenic signaling pathways in various malignancies including neuroblastoma." (PMID 31920463, 2020). "To investigate the association between three AURKA polymorphisms (rs1047972 C>T, rs2273535 T>A, and rs8173 G>C) and neuroblastoma susceptibility in Chinese populations, we performed this two-center case–control study including 393 neuroblastoma cases and 812 controls." (PMID 29678897, 2018). "Moreover, we identify aurora kinase A, a serine/threonine kinase oncogene that is up-regulated in many forms of cancer, including high risk neuroblastoma, as an interaction partner of PTPRD." (PMID 22305495, 2012). "Neuroblastoma (NB) is the most common extracranial solid tumor in children, and the AURKA gene encodes a protein kinase involved in cell cycle regulation that plays an oncogenic role in a variety of human cancers." (PMID 39585848, 2024). "Aurora kinase A (AURKA) is an established oncogenic factorandtherapeutic target in neuroblastoma due to its roles in mitosis andstability of the MYCN protein." (PMID 41252673, 2025). "Complementary evidence from MYCN-amplified neuroblastoma models further supports combining AURKA inhibitors and DDR inhibitors." (PMID 41561634, 2025). "A preclinical study examined the synergistic effects of JQ1 (BRD4 inhibitor) and Alisertib (AURKA inhibitor) in MYCN-amplified neuroblastoma cell lines and mouse models." (PMID 40365336, 2025). "Nonetheless,the optimized compounds SK4454 and SK5527 presented here provide a strong foundation for continued preclinicalstudies aimed at validating AURKA degradation as a therapeutic strategyin neuroblastoma and other AURKA-driven malignancies." (PMID 41252673, 2025). "For example, in MYCN-amplified neuroblastoma cells, Aurora kinase A (AurA) can bind to MYCN and stabilize the protein." (PMID 40365336, 2025).
neuroblastoma (continued). "We aimed to study the impact of AURKA inhibitors on DNA damage and tumor cell death when given in combination with 131I-MIBG therapy in high-risk neuroblastoma." (PMID 38869684, 2024). "The combination of AURKA inhibition with 131I-MIBG treatment is active in resistant neuroblastoma models." (PMID 38869684, 2024). "We aimed to study the impact of AURKA inhibitors on DNA damage and tumor cell death in combination with 131I-MIBG therapy in a pre-clinical model of high-risk neuroblastoma." (PMID 38869684, 2024). "Targets of the aurora kinase A neuroblastoma model are key to AURKA regulation, whose activation is known to correspond to poor prognosis." (PMID 37072458, 2023). "It is known that the AURKA Active node, which is related to AURKA gene of neuroblastoma, is related to poor prognosis." (PMID 37072458, 2023). "Although SC targets tend to have a large number of cycles, the node with the most cycles is rarely a control target, and some control targets are involved in few cycles, such as GWL/MASTL and PP2A in the aurora kinase A neuroblastoma model." (PMID 37072458, 2023). "In neuroblastoma, MYCN maintains stability via binding to Aurora kinase A (AURKA), which inhibits association of Fbw7 to ubiquitinate MYCN." (PMID 36899853, 2023). "To evaluate the performance of the SC approach, we utilized biological networks from literature with known Boolean functions, including cortical area development, T cell differentiation, and aurora kinase A neuroblastoma networks." (PMID 37072458, 2023). "Three update-scheme dependentmodels relevant to this section are the Cell Cycle Transcription by CoupledCDK and Network Oscillators, Aurora Kinase A in Neuroblastoma, and Regulation of the L-arabinose operon inEscherichia coli models." (PMID 38487681, 2023). "Upregulation of AURKA has been reported in various cancers, including neuroblastoma, lymphoma, colorectal, ovarian and prostate cancers." (PMID 36072667, 2022). "Earlier studies demonstrated that BARD1 β blocks the apoptosis of neuroblastoma cells and stabilizes the Aurora kinase A and B, which are essential players in NB biology." (PMID 33530592, 2021). "Low expression of PTPRD mRNA associates with poor disease progression and neuroblastoma patient survival, and a direct role has been proposed for PTPRD in AURKA dephosphorylation and destabilization in neuroblastoma cells." (PMID 34957126, 2021). "In neuroblastoma cells, the mitotic kinase Aurora-A (AURKA), also frequently overexpressed in cancer, prevents N-Myc degradation by directly binding to a highly conserved N-Myc region." (PMID 34884931, 2021). "From this point, MLN8237 combined with AURKA siRNA has a superposition effect on neuroblastoma cells." (PMID 31920463, 2020). "Here, we evaluated the inhibitory effects of AURKA inhibitor MLN8237 on neuroblastoma cells to understand the potential mechanisms responsible for tumor therapy." (PMID 31920463, 2020). "The combination of MLN8237 with AURKA small interfering RNA results in more profound inhibitory effects on neuroblastoma cell growth." (PMID 31920463, 2020). "Herein, we investigated the therapeutic effect of the AURKA inhibitor MLN8237 on neuroblastoma cells in vitro and in vivo." (PMID 31920463, 2020). "We demonstrate that MLN8237, an inhibitor of AURKA, induces the neuroblastoma cell line IMR32 into cellular senescence and G2/M cell phase arrest." (PMID 31920463, 2020). "By contrast, MLN8237 treatment leads to abnormal high expression of AURKA in several neuroblastoma cell lines." (PMID 31920463, 2020). "Because of the abnormal high expression of AURKA in MLN8237-treated neuroblastoma cells, knockdown of AURKA should have an inhibitory effect on cell growth." (PMID 31920463, 2020). "We also investigated AURKA protein level in non-neuroblastoma cell lines including HepG2 and U373 upon MLN8237 treatment." (PMID 31920463, 2020).